INS (insulin)
Diseases named in the same sentence as INS in open-access papers (continued):
Sharing a sentence is not in itself a finding about the gene and the disease.
Insulin resistance (continued). "T2DM is characterized by decreased production and/or availability of insulin, insulin resistance (IR), and hyperglycemia (high blood sugar)." (PMID 26340637, 2015). "Insulin resistance, which can be regarded as the damage of insulin signal transduction, occurs when the normal concentrations of hormone in the circulating are insufficient to regulate metabolic pathways." (PMID 26317832, 2015). "Upon aging, peripheral insulin resistance progressively increases, inducing compensatory chronic elevations in circulating insulin levels." (PMID 25705204, 2015). "For TNFα, our findings are consistent with previous animal studies showing improved insulin sensitivity following deletion of TNFα or TNFα receptors and human studies demonstrating correlation of TNFα with insulin resistance in the Framingham Offspring study." (PMID 26549941, 2015). "Higher visceral adiposity was positively correlated with serum insulin (r=0.376, P<0.05) and homeostatic model assessment insulin resistance (r=0.391, P<0.05)." (PMID 26657014, 2015). "Insulin resistance, a state in which peripheral tissues demonstrate a diminished response to the glucose-lowering properties of insulin, plays a central role in the development of type 2 diabetes mellitus (T2DM)." (PMID 26402673, 2015). "The present study also revealed a higher level of insulin resistance and reduced level of insulin secretion among the NAFLD group of both genders." (PMID 26569494, 2015). "Activation of Liver X receptors (LXRs), key transcriptional regulators of glucose metabolism, normalizes glycemia and improves insulin sensitivity in rodent models with insulin resistance." (PMID 25909991, 2015). "The inability of insulin to perform normal biological functions in vivo is called insulin resistance." (PMID 26843885, 2015). "Recently, effects of adiponectin on peripheral insulin sensitivity also implicate central effects on reduction of high-fat diet-induced hypothalamic inflammation and insulin resistance." (PMID 25705204, 2015). "In the skeletal muscle, fat accumulation reduces translocation of GLUT4 to the plasma membrane in response to insulin stimulation leading to the development of insulin resistance and T2DM." (PMID 26580649, 2015). "Type 2 DM, accounting for 95% of all cases, is a complex metabolic syndrome characterized by hyperglycemia resulting from either insulin resistance or inadequate insulin secretion." (PMID 26258146, 2015). "Studies in insulin-resistant PCOS women suggest that the ovaries remain sensitive to insulin’s actions on steroidogenesis, even when metabolic tissues demonstrate peripheral insulin resistance by decreased glucose disposal." (PMID 26305227, 2015). "In the present study, we sought to examine the effect of TAK-242 and E5564 on insulin action in vivo by utilizing two well-established models of fat-induced insulin resistance (acute lipid infusion and chronic high fat feeding)." (PMID 26196892, 2015). "Activated PKCε inhibits the insulin signaling, consequently resulting in hepatic insulin resistance." (PMID 26633482, 2015). "Per definition, the T2DM group had significantly higher HbA1c % (p<0.001, t-test) and fasting glucose levels than the NGT group, while both groups had abnormally high plasma insulin concentrations and insulin resistance." (PMID 25742416, 2015). "For instance, it has been shown to reduce hyperglycemia and attenuate insulin resistance in part, by inhibiting the ubiquitin-proteasome pathways mediating degradation of insulin receptor substrate 1 and 2, critical mediators of insulin signaling." (PMID 26045713, 2015). "The understanding of the molecular mechanism of insulin action provides a tool to optimize strategies to overcome insulin resistance." (PMID 26383020, 2015). "Elevated insulin levels were observed in the WD-fed groups at the 14-week time point, which when coupled with the unaltered glucose levels, indicates a degree of insulin resistance induced by the high-fat, high-sugar diet." (PMID 25750189, 2015).
Insulin resistance (continued). "We used two types of diabetic mice whose insulin secretion and insulin resistance levels were completely in opposition." (PMID 26606676, 2015). "HF → NC mice showed normal glucose tolerance and higher insulin levels, implying that insulin resistance remained higher than in the NC AL group." (PMID 26445593, 2015). "Type-2 Diabetes (T2D) is characterized principally by insulin resistance in target tissues followed by decreased insulin production due to β-cell failure." (PMID 26469782, 2015). "Glucose intolerance among critically ill patients with severe AKI occurs with significant inhibition of insulin secretion and a state of peripheral insulin resistance on top of insulin resistance from the critical illness." (PMID 25750607, 2015). "Severe insulin resistance is confirmed biochemically in 26 of the subjects by fasting serum insulin (normal range, <150 pmol/L) or postprandial C-peptide/glucose ratio." (PMID 26066530, 2015). "Animals were shown to exhibit enhanced insulin sensitivity, while they become obese and to develop insulin resistance a few weeks later, during hibernation, to finally recover their insulin sensitivity upon awakening." (PMID 25688211, 2015). "Fasting plasma glucose, serum lipids, serum insulin, and expressions of insulin resistance, anthropometry, blood pressure, and magnetic resonance spectroscopy of liver and muscle fat were obtained in 327 Danish children and adolescents aged 8–18 years." (PMID 26252778, 2015). "T2DM is characterized by excessive hepatic glucose release, central obesity, impaired pancreatic insulin secretion and decreased insulin sensitivity by target cells leading to insulin resistance with chronic and persistent hyperglycemia." (PMID 26543713, 2015). "T2DM is a progressive disease, characterized by insulin resistance and impaired insulin secretion, leading to chronic hyperglycemia." (PMID 26359241, 2015). "Insulin resistance is a physiological condition in which cells fail to respond to the normal actions of the hormone insulin." (PMID 25713812, 2015). "The pathophysiology of NODAT closely resembles that of type 2 diabetes mellitus (T2DM), which is characterized by a combination of insulin resistance and insulin hyposecretion." (PMID 25737773, 2015). "This impaired glucose homeostasis results primarily from insulin resistance, as evidenced by the reduced sensitivity to insulin administration in ITT." (PMID 25768847, 2015). "Evidence that individuals with higher insulin resistance also have less endogenous dopamine at D2/3R in the VS would support the modulatory role of insulin signaling on dopaminergic brain reward circuits and food-seeking behaviors." (PMID 25716779, 2015). "The levels of glucose, insulin, and leptin and the homeostasis model assessment for insulin resistance (HOMA-IR) were also significantly elevated in the HFD-OP mice." (PMID 26592433, 2015). "Insulin resistance is characterized by the inability of tissues to respond to insulin, and pancreatic beta cells compensating for this inability by secreting increased amounts of insulin." (PMID 25915047, 2015). "In contrast to early insulin sensitivity, the later part of normal gestation is characterized by maternal hyperinsulinemia and insulin resistance, resulting in increased circulation of lipids and glucose to meet the energy requirements of fetal growth." (PMID 26244062, 2015). "Significant improvements were also observed in the plasma glucose and insulin levels and in the homeostasis model assessment-insulin resistance (HOMA-IR) index for the combination therapy group." (PMID 25789330, 2015). "Through this circuit, mitogenic effects of insulin are not only preserved but are enhanced in Ras/Src-activated cells in the presence of organismal insulin resistance." (PMID 26573956, 2015). "In contrast, increased levels of ROS or prolonged exposure to oxidative stress have been shown to inhibit insulin signaling and to induce insulin resistance." (PMID 25705204, 2015).
Insulin resistance (continued). "The pancreatic beta cell mass changes according to insulin demand, and the condition of insulin resistance requires higher levels of insulin." (PMID 25912041, 2015). "Because obesity leads to insulin resistance, we assessed glucose tolerance and insulin sensitivity in WT and Creb3l4 KO mice." (PMID 26302066, 2015). "Standard medical diagnosis of diabetes, insulin resistance, and other disorders of the energy metabolism include the testing of the glucose-insulin regulatory system, e.g., by an oral or intravenous glucose tolerance test." (PMID 26694479, 2015). "As metabolic syndrome developed in the ZDSD rat, insulin levels increased in a compensatory fashion to combat increasing insulin resistance." (PMID 25961053, 2015). "Increased levels of plasma glucose, insulin, malondialdehyde, tumor necrosis factor-alpha, and insulin resistance and decreased levels of glutathione, glutathione peroxidase, and catalase were found in rats on a high fructose diet." (PMID 25650289, 2015). "In summary, we show that increased intake of sucrose in CBA mice results in rapid development of hyperinsulinemia, hepatosteatosis, and insulin resistance and that insulin enhances hepatic expression of the FA transporter Cd36 in a Pparγ-dependent manner." (PMID 26085100, 2015). "Impairment of insulin biosynthesis and secretion are characteristic of persistent hyperglycemia, leading to insulin resistance 2,3 coupled with oxidative stress 4 and inflammation." (PMID 25726699, 2015). "Peripheral insulin resistance triggers β-cells to produce more insulin in parallel with an increased synthesis of amylin." (PMID 26136651, 2015). "To elucidate the mechanism of insulin resistance in senescent HAECs, we investigated the expression levels of insulin signaling molecules, such as the IR and IRS." (PMID 26338710, 2015). "For diabetic patients, due to low insulin level or insulin resistance, the combining capacity of insulin and insulin receptor is deficient and the effects after combining are limited." (PMID 26246836, 2015). "Insulin resistance (IR) and impaired upregulation of insulin secretion are hallmarks of type 2 diabetes." (PMID 26090471, 2015). "Mean preoperative insulin resistance and BMI were both higher in the groups that had a longer duration of insulin infusion (p = 0.004, p = 0.048)." (PMID 26322019, 2015). "Insulin resistance leads to decreased insulin signaling and, in turn, leads to decreased GLUT4 translocation and glucose transport, which limits the fuel available to muscle for contraction." (PMID 25789156, 2015). "Reproductively, insulin resistance increases hyperandrogenism through insulin increasing ovarian androgen production, and reducing sex hormone-binding globulin (SHBG) production." (PMID 26061015, 2015). "Our findings further revealed that 6 weeks of resistance training with fenugreek seed extract had significant effects on insulin and insulin resistance reduction in diabetic rats." (PMID 26699937, 2015). "To further analyze insulin resistance in the liver, we next analyzed insulin-induced phosphorylation of Akt (p-Akt), downstream mediator in the insulin signalling pathway." (PMID 25757720, 2015). "The fasting insulin concentration (p = 0.0002) and insulin resistance (p = 0.0002) as judged by the HOMA index were significantly reduced after weight loss, although the glucose concentration did not change." (PMID 26623077, 2015). "There is need to further evaluate the potential use of EBN in the management of insulin resistance in already established insulin-resistant conditions." (PMID 26273674, 2015). "The insulin-resistance promotes damage to several insulin-sensitive organs such as liver and kidneys." (PMID 26379553, 2015). "In obese patients, insulin resistance results in an elevated release of peripheral insulin, but insulin concentrations in the brain are reduced, likely due to a decrease in insulin transport across the BBB." (PMID 26217222, 2015).
Insulin resistance (continued). "Insulin resistance is defined as an attenuated biological response of tissues to physiological or elevated levels of insulin." (PMID 26064170, 2015). "According to Neel, thrifty genes have the ability to store fat by producing more insulin during period of famine, when nutrients are limited, but this situation increases the risks of insulin resistance and type 2 diabetes." (PMID 26825664, 2015). "Further, insulin increases ceramide accrual in a time-dependent manner, which is necessary for insulin-induced alterations in heart mitochondrial respiration and insulin resistance." (PMID 26682540, 2015). "After the adjustment for insulin resistance, the insulin secretion indices DI30 and DI exhibited even more significant declining tendencies." (PMID 25664814, 2015). "The genes adiponectin receptor 1, sestrin 3, KCNJ15 and G-protein coupled receptor 27 have all been described to play a role in insulin resistance, decreased insulin secretion and impaired blood glucose homeostasis." (PMID 25768297, 2015). "In line with these early observations, the current view on the human immunology of T2DM is that inflammation links obesity to T2DM, as it mediates the development of obesity-induced insulin resistance in insulin target organs." (PMID 25759846, 2015). "GBD-fed mice showed significantly lower serum insulin levels (p = 0.016) and insulin resistance scores (HOMA-IR) (p = 0.012), suggesting that GBD improved insulin sensitivity." (PMID 25912041, 2015). "Type-2 diabetes is characterized by insulin resistance and the inability of β-cells to upregulate their insulin production." (PMID 26035391, 2015). "Although reductions in insulin and insulin resistance are typically observed post-puberty, we found positive relationships between insulin, insulin resistance and DP z-scores between 14 and 17 y of age." (PMID 26026208, 2015). "The inflammatory cytokines promote insulin resistance by interfering with insulin signaling through activation of JNK kinase and NFκB pathways." (PMID 26300887, 2015). "In humans, the only physiological recovery of insulin sensitivity after a period of insulin resistance, partially due to an increase in food intake and lipogenesis, is observed in women after pregnancy." (PMID 25688211, 2015). "Insulin resistance is defined as a state of decreased responsiveness of target tissues to normal circulating levels of insulin and is the central feature of type 2 diabetes and MetS." (PMID 25774226, 2015). "Insulin resistance was estimated by the homeostatic model assessment index (HOMA-IR) which is based on the calculation of fasting insulin and glucose concentration." (PMID 25786107, 2015). "Obesity-induced hepatic insulin resistance results in expansion of peripheral insulin resistance due to elevated fasting blood glucose and subsequent blood insulin levels." (PMID 26648664, 2015). "There was a significant (p < 0.05) elevation in blood glucose, insulin and insulin resistance in HFD induced obese rats over their normal control rats." (PMID 25887331, 2015). "In the case of insulin resistance, the response of target cells towards insulin is considerably diminished for metabolic (i.e., glucose metabolism) action, but with preserved mitogenic and anabolic actions." (PMID 26521236, 2015). "As serum insulin levels have increased in Fenugreek subjects, insulin resistance was assessed by HOMA." (PMID 26436069, 2015). "CLE significantly decreased fasting blood glucose, glucose level in OGTT and IPITT, plasma insulin, homeostatic model assessment-insulin resistant (HOMA-IR), TNF-α, IL-6, FFA, TG and TC levels, and hepatic glycogen content in db/db mice." (PMID 25889508, 2015). "Insulin resistance and dyslipidemia are characterized by significant downregulation of hepatic insulin signalling as documented by attenuated phosphorylation of IR and IR substrates (IRS)." (PMID 25650336, 2015).
Insulin resistance (continued). "Type 1 diabetes results from the destruction of insulin-producing pancreatic beta cells by a beta cell-specific autoimmune process while type 2 diabetes results from the combination of insulin resistance and inadequate insulin secretion." (PMID 26909308, 2015). "The results showed that HFD worsened metabolic indices and induced insulin resistance partly through transcriptional regulation of the insulin signaling genes." (PMID 26273674, 2015). "According to the results of this study, chemerin level was positively correlated with age, BMI, LDL-C, FBG, and fasting insulin, suggesting the relationship of chemerin with obesity, dyslipidemia, and insulin resistance." (PMID 26170530, 2015). "As a compensatory mechanism, insulin secretion is enhanced in response to insulin resistance to prevent hyperglycemia." (PMID 25855974, 2015). "Here we found reductions in plasma insulin and IGF-1 following CR, strongly impacted on fasting glucose, with insulin also influencing insulin sensitivity and insulin resistance." (PMID 26061745, 2015). "ERα activation with specific agonists reverses high fat diet- (HFD-) induced insulin resistance, whereas ERβ knockout mice display improved insulin sensitivity and glucose tolerance, suggesting that ERα plays a primary role in insulin-glucose homeostasis." (PMID 25883987, 2015). "In these other species, E2 enhances insulin sensitivity, ameliorates insulin resistance, and has a protective effect against the development of type 2 DM." (PMID 26086714, 2015). "Insulin resistance was measured by the Quantitative Insulin Sensitivity Check Index (QUICKI) method." (PMID 26199013, 2015). "This is likely due to the fact that several patients with type 2 diabetes show marked insulin resistance with poor response to insulin treatment." (PMID 26152221, 2015). "In accordance with the impaired whole body insulin resistance, peripheral insulin-target tissues from wild type mice displayed diminished PKB/Akt phosphorylation on HFD." (PMID 26512886, 2015). "While most tissues of animals fed HDS displayed insulin resistance, Ras/Src-activated tumors retained insulin pathway sensitivity and exhibited an increased ability to import glucose." (PMID 26573956, 2015). "Overall, the current and previous results for this model of HFD-induced obesity indicate that these animals develop mild insulin resistance and that plasma glucose levels remain within a physiological range at the expense of increased plasma insulin levels." (PMID 26108563, 2015). "African Americans (AA) have more pronounced insulin resistance and higher insulin secretion than European Americans (Caucasians or CA) when matched for age, gender, and body mass index (BMI)." (PMID 25868721, 2015). "This study provides the first combined evidence that cognitive deficits in the SHR model are accompanied by insulin-signaling dysfunction in the brain in parallel to the existence of peripheral insulin resistance." (PMID 26110057, 2015). "Mice fed with HFD (60% fat kcal) have been found to promote insulin resistance, a phenomenon in which insulin mediation is malfunctioned, but the physiological mechanisms of insulin production are normal." (PMID 26258146, 2015). "Myo-inositol seems to correct the mal-functioning insulin pathways and reduce the signs and symptoms of insulin resistance." (PMID 26351529, 2015). "For example, many mechanistic studies have observed that a HGR diet leads to increased insulin resistance, decreased insulin sensitivity, and/or even disruption of islet architecture." (PMID 26030878, 2015). "To achieve a physiologically relevant approach to impair insulin signalling, we modified a combined insulin + fructose (I/F) treatment protocol, which has previously being used to induce insulin resistance in Chang liver cells." (PMID 26297026, 2015). "HCV genotype 1 is able to directly induce insulin resistance by interfering with insulin signaling on hepatocytes." (PMID 25821463, 2015).